DPP4 (dipeptidyl peptidase 4)
Diseases named in the same sentence as DPP4 in open-access papers (continued):
Sharing a sentence is not in itself a finding about the gene and the disease.
type 2 diabetes (continued). "Circulating DPP-4 activity is significantly elevated in type 1 and type 2 diabetics, which could contribute to the reduction in circulating active GLP-1 and to the consequent hyperglycemia." (PMID 27648071, 2016). "Of medical importance, the discovery of the DPP-4 protease resistant exendin-4 from venom of Heloderma suspectum paved the way for the successful development of GLP-1 analogues as important treatments for insulin resistant type 2 diabetics." (PMID 27898108, 2016). "The, integration of these methods might help to develop a potential DPP-4 inhibitor for treating type-2 diabetes." (PMID 27304951, 2016). "The association between DPP-4 inhibitors and the risk of fracture in patients with type 2 diabetes has not been well established." (PMID 27384445, 2016). "Thus, our present work highlights DPP-4 inhibition as a promising therapeutic strategy for cognitive impairment and cerebral vascular complications in type 2 diabetes." (PMID 25986579, 2015). "Thus, it is important to investigate the efficacy and safety of DPP-4 inhibitors in patients with type 2 diabetes." (PMID 25699116, 2015). "Following identification of the therapeutic effect of glucagon-like peptide-1 (GLP-1), the dipeptidyl-peptidase-4 (DPP-4) inhibitors were developed specifically to delay its rapid degradation in plasma, and hence to enhance the incretin effect in type 2 diabetes (1, –, 3)." (PMID 25664602, 2015). "Thus, glucagon-like peptide-1-based therapies (glucagon-like peptide-1 receptor agonists and dipeptidyl peptidase-4 inhibitors) are now well accepted in the management of type 2 diabetes." (PMID 26366173, 2015). "DPP4 inhibitors may be effectively administered to prevent deterioration in patients with type 2 diabetes in the aftermath of disasters." (PMID 25946187, 2015). "However it has been suggested that DPP-4 inhibitors should be used only for patients with type 2 diabetes who are unable to tolerate other oral antidiabetes medications or who have not managed to achieve the glycemic target with the standard first-line agents." (PMID 26089904, 2015). "Since the incretin hormones, glucagon-like peptide-1 and glucose-dependent insulinotropic polypeptide (GIP), are major regulators of post-prandial insulin secretion, inhibition of DPP4 by the gliptin family of drugs has gained considerable interest for the therapy of type 2 diabetic patients." (PMID 26284071, 2015). "Novel drugs, like selective dipeptidyl peptidase-4 (DPP-4) inhibitors for type 2 diabetes, might have fewer side effects than metformin and other anti-diabetic medication." (PMID 26242578, 2015). "Accordingly, suppressive effect of glucagon by DPP-4 inhibitor may mainly contribute to glucose lowering in longer duration of type 2 diabetes patients with decreased insulin secretion capacities." (PMID 25699116, 2015). "The purpose of the present study was to test our hypothesis that DPP-4 inhibition with linagliptin following short transient cerebral ischemia can counteract cognitive impairment and brain atrophy in obese type 2 diabetes." (PMID 25986579, 2015). "Indeed, it was shown that DPP-4 inhibitors were effective in Japanese type 2 diabetes patients with higher insulin secreting capacities." (PMID 25699116, 2015). "DPP-4 inhibitors have been broadly used as a therapeutic agent for type 2 diabetes." (PMID 25768281, 2015). "In other words, serum AGEs levels may be a clinical biomarker to identify which type 2 diabetic patients will respond less to the treatment with DPP-4 inhibitors." (PMID 25582643, 2015). "In addition, sitagliptin, an inhibitor of DPP-4 was reported to increase circulating EPCs in type 2 diabetic patients with concomitant up-regulation of stromal-derived factor-1α as well." (PMID 25582643, 2015). "Today, DPP4 inhibitors are employed in human medicine to prolong the beneficial incretin effects, in particular to improve insulin sensitivity, with the aim to treat type II diabetes." (PMID 26291537, 2015).
type 2 diabetes (continued). "In addition, levels of MMP-9 were reduced after treatment of linagliptin, an inhibitor for dipeptidyl peptidase-4 enzyme to attenuate aberrant biosynthesis and secretion of insulin to treat Type 2 diabetes." (PMID 25859655, 2015). "However, our study confirmed the effectiveness of DPP-4 inhibitors as the third oral agent in improving glycaemic control in type 2 diabetes." (PMID 25180036, 2014). "Dipeptidyl peptidase-4 (DPP-4) is a new target in the treatment of type II diabetes mellitus." (PMID 24926379, 2014). "The oral DPP-4 inhibitors are new incretin-based therapies for treatment of type 2 diabetes." (PMID 24917890, 2014). "GLP-1 receptor agonists and DPP-4 inhibitors are used to treat type 2 diabetes patients." (PMID 25412338, 2014). "However, intrinsic incretins are rapidly inactivated by DPP-4, and as a result GLP-1 receptor agonists and DPP-4 inhibitors have been developed for the treatment of type 2 diabetes." (PMID 23445717, 2013). "This scenario could support the clinical relevance of blockade of the pathological crosstalk between AGE-RAGE axis and DPP-4 by linagliptin in the treatment with type 2 diabetes." (PMID 23984879, 2013). "Inhibition of dipeptidyl peptidase-4 (DPP-4) is a potential therapeutic target for type 2 diabetes." (PMID 23984879, 2013). "In addition, inhibition of DPP-4 with sitagliptin increased EPCs in 4 weeks in type 2 diabetic patients, possibly through an effect on SDF-1alpha." (PMID 22548049, 2012). "DPP-4 inhibitors represent a valuable new addition to the therapeutic armamentarium to treat patients with type 2 diabetes, providing practitioners with a well-tolerated management option for improving 24-h glycemic control by engaging glucose-dependent physiological processes." (PMID 23554750, 2012). "In conclusion, the present study suggests an additional aspect of how DPP-4 inhibition might contribute to healing of chronic foot ulcers in patients with type 2 diabetes." (PMID 23197976, 2012). "Subsequently treatment protocols for type 2 diabetes have incorporated DPP4 inhibitors." (PMID 22291902, 2012). "In a previous pooled analysis of 12 double-blind clinical studies that included data on 6,139 patients with type 2 diabetes, treatment with sitagliptin, a dipeptidyl peptidase-4 (DPP-4) inhibitor, was shown to be generally well tolerated compared with treatment with control agents." (PMID 20412573, 2010). "In a small network, known causal components ADA and CD26 (DPP4) form a cascade with the predicted causal component CD44 (green node) connected by RANTES (CCL5) (blue node), which harbors promoter polymorphisms associated with type 2 diabetes." (PMID 20815942, 2010). "We first hypothesized that in NAFLD the DPP-4 enzymatic activity is increased which might contribute to the development of type 2 diabetes and metabolic deterioration." (PMID 20805868, 2010). "Incretin-based therapies such as DPP-4 inhibitors have demonstrated the ability to potentiate GABAergic, dopaminergic, serotonergic, and noradrenergic neurotransmission, which are crucial pathways for awakening drugs in both coma and prolonged DOC (see Introduction)." (PMID 39904872, 2025). "This network meta-analysis assesses whether age or sex are associated with differences in the efficacy of sodium-glucose cotransporter 2 inhibitors, glucagon-like peptide-1 receptor agonists, and dipeptidyl peptidase 4 inhibitors in adults with type 2 diabetes." (PMID 39899304, 2025). "This network meta-analysis of 601 trials, including individual participant data from 103 trials, assessed whether the efficacy of 3 newer drug classes (SGLT2 inhibitors, GLP-1 receptor agonists, and DPP4 inhibitors) varied by age or sex in people with type 2 diabetes." (PMID 39899304, 2025). "Administration of DPP-4 inhibitors does not cause hypoglycemia in type 2 diabetes patients." (PMID 40734861, 2025).
type 2 diabetes (continued). "Similarly, a large multicenter real-world study involving type 2 diabetes patients in Canada and the UK found that SGLT2i treatment did not increase the risk of urosepsis compared to DPP-4 inhibitors." (PMID 39882521, 2024). "However, ongoing vigilance is necessary to understand fully the nuanced effects of DPP-4 inhibitors on heart failure, making EXAMINE a critical foundation for future research and clinical decision-making in the management of type 2 diabetes and cardiovascular risk." (PMID 39768866, 2024). "Similarly, investigations indicated that transferring fecal samples from type 2 diabetes patients treated with DPP-4 inhibitors into germ-free mice improved glucose tolerance, particularly in response to impairments induced by high-density lipoprotein cholesterol." (PMID 39735647, 2024). "However, whether an improvement in beta-cell function observed in type 2 diabetes after switching from a DPP-4 inhibitor to a GLP-1R agonist is also found in PNDM remains unclear." (PMID 39430732, 2024). "DPP-4 inhibitors are a class of relatively new oral anti-hyperglycemic agents indicated for patients with Type 2 Diabetes Mellitus (T2DM)." (PMID 38069152, 2023). "Moreover, CD26/DPP-4 inhibitors have been assessed and investigated for their nephroprotective role in glycemic management to reduce the incidence of micro- or macroalbuminuria in type 2 diabetes patients." (PMID 37627907, 2023). "Does the effectiveness and safety of sodium-glucose cotransporter 2 inhibitors (SGLT2i) differ from that of dipeptidyl peptidase 4 inhibitors (DPP-4i) in patients with type 2 diabetes (T2D) overall and at varying baseline hemoglobin A1c (HbA1c) levels?" (PMID 36745425, 2023). "Therefore, until drugs effective against COVID-19 viruses are developed, drugs for type II diabetes such as DPP4 inhibitors and GLP-1 may protect COVID-19 patients from severe symptoms by improving endothelial damage and inhibiting EndoMT." (PMID 35130955, 2022). "Thus DPP4 may be a potential target for the treatment or prevention of COVID-19 patients with concomitant type 2 diabetes." (PMID 36329841, 2022). "In addition to autoimmune disease, immune cell-derived DPP4 may also other disease conditions such as type 2 diabetes." (PMID 35309368, 2022). "From a type 2 diabetes (T2DM) treatment standpoint, metformin, Dipeptidyl peptidase 4 inhibitors (DPP4i), and sulfonylureas (SU’s) are therapeutically equivalent." (PMID 36395143, 2022). "In this cross-sectional study, in patients with type 2 diabetes and stage 5 CKD or ESKD, use of GLP-1 receptor agonists was associated with better outcomes, including all-cause mortality and sepsis- and infection-related mortality, compared with use of DPP-4 inhibitors." (PMID 35254430, 2022). "However, DPP4 may illustrate a potential target for decreasing the progression of the complications of type 2 diabetes in those infected with COVID-19." (PMID 34068970, 2021). "Accordingly, excess DPP4 derived from adipocytes and/or hepatocytes may act as a local mediator of inflammation and adipose/hepatic tissue insulin resistance, thereby forming a link between obesity and the pathogenesis of type 2 diabetes and metabolic disease." (PMID 33691757, 2021). "However, there has been no clear evidence to support the inhibition of cardiovascular events or diabetic nephropathy by DPP-4 inhibitors, although the glucose-lowering efficacy of DPP-4 inhibitors in patients with type 2 diabetes is better in Asians than in other ethnic groups." (PMID 33720983, 2021). "The expression of DPP-4 gene was disrupted in type 2 diabetes mellitus (T2DM) db/db mice with remarkable efficacy." (PMID 34683943, 2021). "However, the generalisability of these results does not necessarily extend to those at higher risk for cognitive decline, or to those with MMSE <24, and we also cannot extrapolate the results to individuals with more advanced type 2 diabetes, or to other DPP-4 inhibitors or sulfonylureas." (PMID 33559704, 2021).
type 2 diabetes (continued). "DPP-4 inhibitors may improve the mortality of patients with COVID-19 and type 2 diabetes." (PMID 34015003, 2021). "Thus, DPP-4 inhibitors are promising candidates for treating type 2 diabetes." (PMID 32282828, 2020). "Reportedly, DPP-4 inhibitors might ameliorate NAFLD in patients with type 2 diabetes." (PMID 33105604, 2020). "Another epidemiological study including 403 hospitalized COVID-19 patients found that DPP4 inhibitors might not affect the risk of hospitalization for COVID-19 patients with type 2 diabetes." (PMID 33584268, 2020). "Therefore, DPP-4 inhibitors could be a novel preventive option for oxaliplatin-induced chronic peripheral neuropathy in patients with type 2 diabetes." (PMID 32317735, 2020). "Consequently, there are some essential issues to be addressed before claiming possible beneficial effects of DPP4 inhibitors on COVID-19, and the effects of DPP4 inhibitors in patients with type 2 diabetes and COVID-19 should be confirmed in an ongoing randomized, placebo-controlled trial." (PMID 33584268, 2020). "The DPP-4 inhibitors developed for the treatment of type II diabetes, as well as α-thrombin and Factor Xa inhibitors used as anti-coagulants, may not be appropriate for patients who do not suffer such problems but may be useful for patients who need such treatment." (PMID 32485894, 2020). "DPP4 inhibitors are thereby clinically used as “incretinergic” drugs for type 2 diabetes mellitus (T2DM)." (PMID 31402899, 2019). "Here we aim to decipher the role of enhanced plasma DPP4 activity in obese type 2 diabetes (T2DM) patients." (PMID 31402899, 2019). "The systemic inhibition of DPP4 by marketed drugs named gliptins, is being successfully used for reduction of hyperglycemia in type 2 diabetes (T2D) patients." (PMID 31794591, 2019). "Besides the development of various efficient DPP-4 inhibitors and the demonstration that they have glucose-lowering properties, an important factor behind the concept of DPP-4 inhibition was that it targets the basic pathophysiological processes in type 2 diabetes." (PMID 31275243, 2019). "Across a series of new-user cohorts consisting of patients with type 2 diabetes in the UK, we found that the incidence of acute kidney injury, respiratory tract infections, and acute pancreatitis were 4.8, 104, and 0.9 per 1,000 patient-years, respectively, among initiators of a DPP4 inhibitor." (PMID 30310100, 2018). "The dipeptidyl peptidase-4 (DPP4) inhibitor sitagliptin, which enhances the bioavailability of incretin hormones, improves both glucose tolerance and lipid metabolism in individuals with type 2 diabetes, thereby targeting both microvascular and macrovascular complications." (PMID 30145664, 2018). "Dipeptidyl peptidase-4 (DPP-4) inhibitors are oral anti-hyperglycemic drugs enabling effective glycemic control in type 2 diabetes (T2D)." (PMID 28160554, 2017). "In addition, our finding of a markedly distinct HbA1c response in different HGI subgroups is also consistent with a former study, which suggested that baseline HbA1c was an important predictor of HbA1c response to DPP-4 inhibitors in patients with type 2 diabetes." (PMID 28182722, 2017). "Preserving GLP1 via DPP4 inhibition stimulates insulin secretion and has therefore been the recent focus for treatment of type 2 diabetes mellitus (T2DM)." (PMID 29253907, 2017). "Thus, we asked whether genetic variation in the DPP4 gene affects incretin levels, insulin secretion, and glucose tolerance in participants of the TÜbingen Family study for type-2 diabetes (TÜF)." (PMID 28750074, 2017). "Dipeptidyl peptidase-4 inhibitors (DPP-4i) are routinely used for the treatment of type 2 diabetes (T2D)." (PMID 28183314, 2017). "The DPP-4 inhibitor prolongs the action of incretin hormones by inhibition of their breakdown and improves glycemic control through incretin hormone-induced decrease in glucagon levels and increase in endogenous insulin secretion in patients with type 2 diabetes." (PMID 27624168, 2016).
type 2 diabetes (continued). "However, the long-term effect of a DPP-4 inhibitor on FMD in patients with type 2 diabetes remains unclear." (PMID 27624168, 2016). "Other anti-diabetic drugs, such as dipeptidyl peptidase-4 (DPP-4) and alpha-glucosidase inhibitor could also improve endothelial function in patients with type 2 diabetes, rosiglitazone could improve angiogenic potential of diabetic ECs and proangiogenic cells (PACs)." (PMID 27316923, 2016). "A computational approach involving molecular docking refined with molecular dynamics simulations as well as a pharmacophore analysis could pave the way for new insights on potential DPP-4 inhibitors for type-2 diabetes treatments, as successfully described in the literature about other case studies." (PMID 27304951, 2016). "However, the SAVOR-TIMI-53 trial and another meta-analysis suggested that DPP-4 inhibitors could increase the rate of hospitalization for heart failure in patients with type 2 diabetes." (PMID 26759813, 2016). "Therefore, DPP-4 is a well-documented drug target for the treatment of type 2 diabetes." (PMID 26877767, 2016). "Dipeptidyl peptidase 4 inhibitors like Sitagliptin, Vildagliptin, and Saxagliptin are currently in use to treat patients with type 2 diabetes mellitus (T2DM)." (PMID 25852751, 2015). "However, it remains to be defined whether DPP-4 inhibitor administration following short transient cerebral ischemia can counteract cognitive impairment and brain injury in type 2 diabetes." (PMID 25986579, 2015). "Treatments with DPP4 inhibitors have been investigated for their ability to enhance engraftment following umbilical cord blood transplantation in adults with hematologic malignancies, to improve endothelial dysfunction, and to prevent major cardiovascular events in patients with type 2 diabetes." (PMID 26021829, 2015). "As first line therapy, DPP-4 inhibitors can be an alternative therapeutic option in patients who cannot tolerate metformin because of gastrointestinal adverse events, and several clinical studies have proved their efficacy as monotherapy in drug-naïve patients with diabetes type 2." (PMID 26355765, 2015). "Therefore, we propose that DPP-4 inhibition may be a promising strategy for prevention and treatment of ischemic brain injury and cognitive decline in type 2 diabetes." (PMID 25986579, 2015). "Therefore, SU and DPP4 inhibitor may be an effective combination for supporting inappropriate insulin secretion in type 2 diabetes." (PMID 24578754, 2014). "Thus, data suggest that compared to placebo the DPP-4 inhibitor saxagliptin may reverse early hemodynamic and vascular remodeling processes in type-2 diabetes." (PMID 24423149, 2014). "Adults with type 2 diabetes and BMI ≤30 kg/m2 initiating GLP-1 RAs or dipeptidyl peptidase-4 inhibitors (DPP-4i) between 2016 and 2023 were identified." (PMID 42080079, 2026). "Dipeptidyl peptidase 4 inhibitors (DPP-4i), also known as gliptins, are oral antihyperglycemic drugs used in the pharmacological treatment of type 2 diabetes mellitus (T2DM)." (PMID 41471289, 2025). "Here we overview the glucose-lowering and weight-reducing effects of incretin-based therapies, discussing the effective and safety use of DPP-4 inhibitors, GLP-1 RAs, and GIP/GLP-1 receptor agonist tripeptide in Japanese individuals with type 2 diabetes." (PMID 40607140, 2025). "Patients with type 2 diabetes who were treated with metformin and additionally received either an SGLT2 inhibitor or a dipeptidyl peptidase-4 (DPP4) inhibitor were included." (PMID 40863028, 2025). "Given the significance of DPP4 in glucose regulation, DPP-4 inhibitors have emerged as promising therapeutic agents for treating type-2 diabetes." (PMID 40904650, 2025). "For example, linagliptin, a dipeptidyl peptidase-4 (DPP-4) inhibitor and FDA-approved glucose-lowering drug for type 2 diabetes, have shown reno-protective effects in rodent models of both non-diabetic as well as diabetic kidney disease." (PMID 41074478, 2025).